EGFR (epidermal growth factor receptor)
Diseases named in the same sentence as EGFR in open-access papers (continued):
Sharing a sentence is not in itself a finding about the gene and the disease.
tumor (continued). "Some markers, like HER2 and EGFR are expressed at higher levels in cancer cells as compared with normal cells in certain tumor types." (PMID 25527469, 2014). "Our findings reveal that PHD3 inactivation provides an alternative route of EGFR activation through which tumour cells sustain proliferative signalling even under conditions of limited oxygen availability." (PMID 25420773, 2014). "Experimental evidences that the tumor microenvironment plays a significant role in resistance of EGFR inhibitor have been reported." (PMID 25240937, 2014). "In addition, oncogenic driver mutations may be tumor specific, as different driver mutations from different tumor sites within the same individual have been identified in patients with EGFR-TKI resistant disease, further illustrating the challenges in managing patients with acquired resistance." (PMID 25101246, 2014). "In EGFR-mutated lung cancer cell lines (PC-9 and HCC827), icotinib showed similar anti-tumor effect compared with gefitinib." (PMID 24836053, 2014). "GBM is a tumor characterized by heterogeneous features with different regional expressions of potential therapeutic targets such as EGFR and VEGF." (PMID 24675671, 2014). "EGFR activation leads to tumor cell survival, aberrant cell cycle and evasion of apoptosis, ultimately leading to resistance to cytotoxic therapies." (PMID 24811863, 2014). "Except degradation of IRS-1, NE also cleaves pro-TGF-α to release mature TGF-α in gastric TMK-1 cells, which activates EGFR-induced tumor proliferation." (PMID 24457622, 2014). "These novel findings lend support to the suggestion that LRIG1 acts as a tumor suppressor and negative regulator of EGFR." (PMID 24709893, 2014). "These contrasting findings suggest that while BC cells utilize EGFR signaling to facilitate certain aspects of tumor progression, they become inherently resistant to inhibition of EGFR function during the later stages of disease progression." (PMID 25255930, 2014). "The anti-EGFr-AuNP conjugates were injected intravenously via tail vein and showed tumor localization." (PMID 24520385, 2014). "Densitometry of relative RT-PCR EGFR tumor transcripts were significantly decreased compared to normal lung EGFR message, whereas transcripts for ALK were significantly increased in tumors compared to the corresponding normal tissue ALK message (n = 3)." (PMID 24423144, 2014). "Ten variants were identified from eight genes in both the tumor and normal groups (APC, EGFR, FGFR3, KDR, MET, PDGFRA, RET and SMO)." (PMID 25404506, 2014). "When monolayer or spheroid cultures were stimulated with EGF or HGF, all of the tumor cell lines, cultured as 3D spheroids, were less responsive to growth factor stimulation (phosphorylation of EGFR and cMET, respectively) than cells grown as 2D monolayers." (PMID 24638075, 2014). "The tumors obtained from mice treated with EGFR-targeted system show minimum mass, which was consistent with the trend obtained from tumor volume measurements." (PMID 24507760, 2014). "Activated EGFR recruits downstream signaling molecules, leading to the activation of different pathways important in tumor growth, progression, and survival." (PMID 25563226, 2014). "In the presence of resistance, some tumor cells retain their original sensitive mutant and can still clone using the EGFR pathway." (PMID 25610713, 2014). "In the light of recent findings on the role of some molecular markers in the pathogenesis and progression of this tumor, we have also carried out molecular analyses to verify the methylation of p16 promoter and mutational status of KRAS, PIK3CA and EGFR." (PMID 25358264, 2014). "Anti-EGFr antibody was adsorbed to gold nanorods and incubated in vitro with epithelial tumor or non-tumor cells." (PMID 24520385, 2014). "To date, the tumor suppressing function of LRIG1 has mainly been attributed to its inhibitory effect on EGFR signaling." (PMID 24709893, 2014).
tumor (continued). "Anti-tumor effects of gefitinib and erlotinib have been investigated in other EGFR+ tumors, including gastric, gastroesophageal, esophageal, cervical, renal cell carcinoma, and hepatocellular carcinoma." (PMID 25110867, 2014). "Immunohistochemistry studies showed that EGF Receptor (EGFR) over-expression positively correlates with advanced tumour staging and lymph node metastasis." (PMID 25510623, 2014). "The protein expression of SphK1 and EGFR in the tumor tissues from 180 patients was analyzed and compared to the expression in non-cancerous tissues." (PMID 25245676, 2014). "Other recent studies have also shown that miR-146a negatively regulates EGFR expression and inhibits tumor growth through the MAPK kinase pathway in a p-ERK-dependent manner to control cell migration, proliferation, and morphogenesis." (PMID 25490205, 2014). "TUNEL staining performed on sections of the tumor also confirmed that EGFR-targeted nanoparticle treated tumor section show highest population of cells undergoing apoptosis (brown TUNEL positive cells) compared to those treated with SH-Gel and SH-Gel-PEG." (PMID 24507760, 2014). "Mortality was found to be influenced by c-Kit and/or EGFR expression in the tumor, with patients with c-Kit-positive tumors found to have an increased mortality rate compared with those with c-Kit-negative tumors, 30 months post-surgery." (PMID 25013472, 2014). "In agreement with in vitro studies, tumor growth induced by NTS/NTSR1 can be restrained by a specific tyrosine kinase inhibitor EGFR and HER2, lapatinib." (PMID 25249538, 2014). "Targeting tumor cells with the EGFR inhibitor erlotinib followed by radiation delayed tumor re-growth to a greater extent than radiation alone." (PMID 24717239, 2014). "Inhibition of EGFR+ tumor cell growth by AvidinOX-anchored anti-EGFR antibodies correlated with increased induction of apoptosis." (PMID 25238453, 2014). "Looking at the published or presented results, most trials suggest no role or, at best, slightly better outcome for patients with EGFR mutant tumor when treated with first-line CT." (PMID 25300933, 2014). "Here, for one tumor, EGFR increased copy number was restricted to the solid counterpart as compared to lepidic pattern." (PMID 24885034, 2014). "The role of tumor EGFR expression in predicting benefit from adding cetuximab in NSCLC is under investigation." (PMID 24386952, 2014). "EGFR also functions in chemotherapeutic resistance and radiation tolerance in tumor cells, in which multiple downstream pathways of EGFR, including RAS-RAF-MAK-MAKP, PI3K/AKT, and STAT, are activated." (PMID 25289099, 2014). "EGFR is a membrane growth factor receptor that plays a role in tumor cell proliferation, adhesion, invasion and apoptosis suppression and increase angiogenesis." (PMID 24743427, 2014). "(ii) Apart from its effect on EGFR degradation, PI4KIIα inhibition directly interferes with the PI3K/AKT pathway, thus the combined inhibition of PI4KIIα and EGFR results in a triple anti-tumor effect." (PMID 24801752, 2014). "In previous experiments an enhanced anti-proliterative effect of the EGFR/ErbB tyrosine kinase inhibitor (TKI) BIBW 2992 with single dose irradiation was observed in FaDu tumour xenografts." (PMID 25444177, 2014). "Evidence supports investigation of positron emission tomography (PET) with F-18 fluorodeoxyglucose (FDG)-PET/CT to evaluate tumor response to EGFR inhibitors." (PMID 25081631, 2014). "We found higher EGFR expression in both tumor and CTCs from sample C22 and C23 compared with healthy control." (PMID 25474037, 2014). "Inhibition of the downstream signaling components of EGFR, such as Erks and Akt, was also thought to be a candidate to block tumor growth, but this greatly affects the survival and functions of most normal cells and hence often evokes severe side effects." (PMID 24621372, 2014).
tumor (continued). "Growth factor receptors, including the epidermal growth factor receptor (EGFR), are often overexpressed and/or mutated in NSCLC and regulate oncogenic processes including tumor cell proliferation, migration and EMT transition." (PMID 24662916, 2014). "Overexpression of EGFR provides tumour cells with growth and survival advantages, and this process is thought to substantially contribute to the aggressive nature of cancer cell proliferation." (PMID 24973959, 2014). "An EGFR inhibitor erlotinib was used to assess the modulation of anti-tumor responses by tumor antigen-specific helper T cells." (PMID 25240937, 2014). "The average response to EGF across all cell lines in a 2D monolayer was a 2.67 fold increase in EGFR phosphorylation, while there was only a 1.5 fold increase in tumor spheroid cell lines." (PMID 24638075, 2014). "We then evaluated the anti-tumor efficacy of an EGFR endocytosis inhibitor in vitro using a mouse xenograft model." (PMID 24658031, 2014). "Taken together, the data indicate that both the EGFR and Aurora kinases seem to play important roles in the tumour biology and treatment of HNSCC." (PMID 24980817, 2014). "Activation of downstream signal pathways of epidermal growth factor receptor (EGFR) family is known to mediate HBx-dependent HCC tumor progression." (PMID 24719890, 2014). "The clinical criteria used to propose these therapies are based on the detection of genetic defaults in the tumor (HER2 amplification, EGFR mutation)." (PMID 25249545, 2014). "In xenograft experiments, inoculated EGFR-overexpressing NSCLC cells showed tumor regression when treated with the inhibitor, demonstrating the chemotherapeutic potential of this agent." (PMID 25321484, 2014). "EGFR mutations were identified by NGS in CTC preparations of 31 (84%) patients, corresponding to those present in matching tumor tissue." (PMID 25137181, 2014). "Erlotinib inhibits tumor growth by inhibiting EGFR autophosphorylation to block its downstream signal transduction." (PMID 25000529, 2014). "The blocked crosstalk of EGFR and c-Met was also contributed to the prominent anti-tumor effect of MTE → MTE + Gef treatment." (PMID 24884778, 2014). "The present study aimed to investigate the prognostic impact of c-Kit and/or EGFR expression in tumor tissue samples from 146 patients with NSCLC." (PMID 25013472, 2014). "The major intertumoural heterogeneity of the antiproliferative effect is in line with previous experience on the selective EGFR-TK inhibitor erlotinib in 5 different tumour models." (PMID 25444177, 2014). "Numerous types of tumor express the epidermal growth factor receptor (EGFR), which regulates cell proliferation, migration and differentiation." (PMID 25013472, 2014). "This strongly suggests that combined inhibition of Bcl-xL and EGFR is likely to achieve synergistic anti-tumor effects." (PMID 24621885, 2014). "Some studies have shown that EGFR plays an important role in angiogenesis, tumor cell metastasis and apoptosis." (PMID 25000529, 2014). "Like EGFR expression, the co-expression of EGFR/HER-4 was also significantly associated with patients over 70 years old (P = 0.031) and presenting tumours in the left colon (P = 0.039) in this study." (PMID 24609222, 2014). "Dual targeting of EGFR using cetuximab and gefitinib has displayed synergic effects on inhibition of tumor cell proliferation and prevented drug resistance in colon cancer cell lines." (PMID 25110867, 2014). "We recently reported the capacity of EGFR inhibitors to augment HLA-DR surface expression on tumor cells." (PMID 25240937, 2014). "MMPs can contribute to tumor cell proliferation by altering the bioavailability of growth factors, such as insulin growth factors (IGFs) and the epidermal growth factor receptor (EGFR) ligands." (PMID 24578639, 2014). "At diagnosis, only 3 patients (11.5%) with EGFR mutated tumours had BM as the only metastatic site, while there were 22 (34%) such patients in EGFR wild type tumours (p = 0.029)." (PMID 24991207, 2014).
tumor (continued). "Previous studies have shown that the EGFR inhibitor erlotinib (TarcevaTM) significantly inhibited cell motility, invasiveness, tumor growth, and spontaneous lung metastasis in EGFR-expressing IBC models." (PMID 24886365, 2014). "In this article we show that the NTS/NTSR1 complex enhances tumor aggressiveness (tumor growth and metastasis emergence) by enhancing HERs expression, and their activation by the release of specific EGFR and HER3 ligands." (PMID 25249538, 2014). "We have recently reported the use of EGFR inhibitors as an adjunct treatment to enhance HLA-DR expression in tumor cells to improve cancer immunotherapy." (PMID 25240937, 2014). "We found that EGFR inhibition at both protein and activity level via combinatorial blocking of PI4KIIα proved superior as a strategy to suppress EGFR-dependent tumor growth." (PMID 24801752, 2014). "All the results indicated that activation of AMPK by metformin potentiated dasatinib-induced ER stress, EGFR degradation, and anti-tumor effect in vivo (schematic illustration)." (PMID 24457597, 2014). "Our results also demonstrated that docetaxel followed by gefitinib (D→G) was significantly superior to other modes in regard to the anti-tumor effects not only in EGFR mutant and K-ras WT PC-9 cells, but also in EGFR WT and K-ras mutant A549 cells." (PMID 25474307, 2014). "Presence of EGFR-targeting peptide on the surface however did result in a higher nanoparticle accumulation in the tumor indicating potential therapeutic advantage." (PMID 24507760, 2014). "It inhibits EGFR and HER2 tyrosine phosphorylation at the TK domain and prevents the activation of ERK1/2 and AKT followed by apoptosis of tumor cells in vitro and in vivo in xenografted mice with cell lines over-expressing EGFR and HER2." (PMID 25110867, 2014). "The immunohistochemical panel showed strong positivity for p63 and EGFR in the epithelial component of the tumor, while p16 was positive in the basal, parabasal and intermediate layer of the papillary epithelial component." (PMID 25358264, 2014). "Consistent with this pattern, treatment of animals bearing EGFR-driven tumours with a specific kinase inhibitor was more effective if administered during the resting phase of the day, when glucocorticoids are low." (PMID 25278152, 2014). "Here we examined the regulatory mechanisms by which PI4KIIα controls EGFR protein levels, and tested the effect of dual inhibition of PI4KIIα and EGFR on tumor growth." (PMID 24801752, 2014). "The two remaining genes encode for EGFR and TFRC, two sialoglycoproteins equally expressed in the tumor group and the astrocyte group." (PMID 25360666, 2014). "In these studies, only the simultaneous blockade of both MET and EGFR effectively impaired tumor growth in vivo." (PMID 24811491, 2014). "Currently, the treatment’s choice is based on a careful assessment of tumor histology and, most importantly, of biological characteristics, specifically of the EGFR and ALK status." (PMID 25505694, 2014). "So far, determination of EGFR status was performed by immunohistochemistry on paraffin-embedded tumor specimens to select patients suitable for EGFR-specific therapies." (PMID 25227424, 2014). "EGFR tyrosine-kinase inhibitors (TKIs) can inhibit tumor cells by blocking the EGFR signaling via binding to ATP binding site on the tyrosine kinase domain of the EGFR." (PMID 24836053, 2014). "The OSCC tumor tissue samples had stronger EGFR, C/EBPβ and miR-31 expression than the NCOM samples." (PMID 25229239, 2014). "In humans, DACH1 is known to repress tumorigenesis in human breast and prostate cancers and down regulates EGFR and cyclin D1 in tumour cells." (PMID 24392136, 2014). "CXCL8 (interleukin-8) was involved in tumor cell proliferation via the transactivation of the epidermal growth factor receptor (EGFR)." (PMID 24629040, 2014). "It is known that epidermal growth factor receptor (EGFR) play important roles in tumor proliferation, invasion, and metastasis." (PMID 24602316, 2014).
tumor (continued). "Specifically, does tissue stiffening modulate, potentiate, or otherwise interact with EGFR-based signaling to drive tumor cell proliferation?" (PMID 25000176, 2014). "Several proteins, such as ER and EGFR, are currently evaluated in cancer diagnosis, and the correlation between their expression and tumor stage, differentiation degree or aggressiveness led also to their use in prognostic applications." (PMID 24899248, 2014). "The third-generation EGFR-TKIs, CO-1686 and AZD9291, demonstrated anti-tumor activity in both sensitizing and resistant EGFR mutation tumors in preclinical models." (PMID 25563355, 2014). "Our study suggests that Matn2 functions as a tumor suppressor in hepatocarcinogenesis, and in this process activation of EGFR together with that of Erk1/2, as well as inactivation of GSK-3β, play strategic roles." (PMID 24691449, 2014). "Overexpression of SGLT-1 is a survival strategy utilized by several tumor types, including EGFR-positive tumors." (PMID 24495286, 2014). "The combination of cetuximab and trastuzumab had a synergistic anti-tumor effect that was mainly due to the modification of the distribution of homo- and hetero-dimers, with disruption of EGFR/HER2 dimers and increased homodimer formation." (PMID 25216528, 2014). "Studies have revealed a histological transformation from NSCLC into SCLC in combination with alterations of tumor markers in EGFR mutant patients who acquired EGFR-TKI resistance." (PMID 24396447, 2014). "Combined inhibition of PI4KIIα and EGFR displayed far superior anti-tumor traits than single drug use, both in terms of tumor volume and weight." (PMID 24801752, 2014). "This independent series comprised 33 GBMs from the Salpêtrière database treated with the combination of bevacizumab/irinotecan at recurrence and for whom the CDKN2A locus homozygous deletion and EGFR amplification status were available in the initial tumor." (PMID 24804210, 2014). "Evidence has revealed that tumor response and patient survival have improved in the present and increased severity rash from EGFR inhibitors." (PMID 24723942, 2014). "It is known that EGFR stimulate DSB repair after irradiation or activation by its ligands and that the ability of tumor cells to repair DNA damage is reduced following EGFR blockade with Cetuximab." (PMID 25409711, 2014). "Another study investigated the relation between the in vivo expression of EGFR and the tumor uptake of 89Zr-cetuximab." (PMID 24991539, 2014). "The receptor tyrosine kinases EGFR and ERBB2, the GTPases KRAS, NRAS, and HRAS, and the kinase BRAF are frequently mutated in cancers and can drive tumor proliferation." (PMID 24874471, 2014). "Looking at the co-expression of receptors, only EGFR/HER-4 immunostaining at above 5% tumour cells remained as an independent prognostic factor for poor disease-free survival in this study." (PMID 24609222, 2014). "Here we identify PHD3 as a novel regulator of EGFR activity that limits tumour proliferation and survival in response to growth inhibitory cues." (PMID 25420773, 2014). "Conversely, production of transforming growth factor beta (TGF-β) and prostaglandin E2 was increased by EGFR inhibition, indicating that these immunosuppressive molecules were involved in diminishing tumor recognition by T cells." (PMID 25240937, 2014). "Kras provided the tumor cells with the ability of self-sustaining proliferative signals by up-regulating EGFR, Raf-MEK-ERK, PI3K-AKT-mTOR and GSK3 signaling pathways." (PMID 24633177, 2014). "The staining pattern for EGFR was mainly membranous and cytoplasmic and tumor AQUA scores ranged between 2.64 and 62.9." (PMID 24722213, 2014). "For example, tumor cell uses an alternative signaling such as HER-3 when EGFR signaling is inhibited, suggesting that tumor cells can transform their function to adapt to the surrounding microenvironment." (PMID 25240937, 2014).